VPS29 (VPS29 retromer complex component)
Description:
Component of the commander complex that is essential for endosomal recycling of transmembrane cargos; the commander complex is composed of the CCC subcomplex and the retriever subcomplex. Component of the retriever complex, which is a heterotrimeric complex related to retromer cargo-selective complex (CSC) and essential for retromer-independent retrieval and recycling of numerous cargos such as integrin alpha-5/beta-1 (ITGA5:ITGB1). Component of the retromer cargo-selective complex (CSC). The CSC is believed to be the core functional component of retromer or respective retromer complex variants acting to prevent missorting of selected transmembrane cargo proteins into the lysosomal degradation pathway. The recruitment of the CSC to the endosomal membrane involves RAB7A and SNX3. The SNX-BAR retromer mediates retrograde transport of cargo proteins from endosomes to the trans-Golgi network (TGN) and is involved in endosome-to-plasma membrane transport for cargo protein recycling. The SNX3-retromer mediates the retrograde endosome-to-TGN transport of WLS distinct from the SNX-BAR retromer pathway. The SNX27-retromer is believed to be involved in endosome-to-plasma membrane trafficking and recycling of a broad spectrum of cargo proteins. The CSC seems to act as recruitment hub for other proteins, such as the WASH complex and TBC1D5. Required to regulate transcytosis of the polymeric immunoglobulin receptor (pIgR-pIgA). In the endosomes, retriever complex drives the retrieval and recycling of NxxY-motif-containing cargo proteins by coupling to SNX17, a cargo essential for the homeostatic maintenance of numerous cell surface proteins associated with processes that include cell migration, cell adhesion, nutrient supply and cell signaling. The recruitment of the retriever complex to the endosomal membrane involves CCC and WASH complexes. Involved in GLUT1 endosome-to-plasma membrane trafficking; the function is dependent of association with ANKRD27. (Microbial infection) The heterotrimeric retromer cargo-selective complex (CSC) mediates the exit of human papillomavirus from the early endosome and the delivery to the Golgi apparatus.
Synonyms: DC15; DC7; PEP11
Tractability: Small molecule: a structure with a bound ligand is known. Antibody: UniProt places it where antibodies can reach, with medium confidence. PROTAC: ubiquitination databases record sites on it; its protein half-life has been measured.
Gene: Protein-coding gene on chromosome 12 (110,491,083 to 110,502,111, reverse strand). Ensembl gene ENSG00000111237.
Subcellular location: Cytoplasm; Membrane; Endosome membrane; Early endosome; Late endosome
Subcellular location (Human Protein Atlas): Cytosol; Vesicles
Pathways (Reactome):
Signal Transduction: WNT ligand biogenesis and trafficking
Gene Ontology:
Molecular function: protein binding; cargo adaptor activity
Biological process: endocytic recycling; regulation of autophagy; retrograde transport, endosome to Golgi
Cellular component: cytosol; endosome; protein-containing complex; retromer complex; retromer, cargo-selective complex; endoplasmic reticulum membrane; endosome membrane; cytoplasm; early endosome; late endosome; membrane
Genetic constraint (gnomAD): Loss-of-function variants: 2 observed, 17.73 expected, observed/expected ratio (o/e) 0.11, 90% interval 0.045 to 0.35. The upper end of that interval is the gene's LOEUF score, 0.35, which puts it in group 1 of 6, group 1 being the genes least tolerant of losing a copy. Missense variants: 112 observed, 211.04 expected, observed/expected ratio (o/e) 0.53, 90% interval 0.45 to 0.62. Synonymous variants: 78 observed, 79.14 expected, observed/expected ratio (o/e) 0.99, 90% interval 0.82 to 1.19.
Homologues: Orthologues: chimpanzee VPS29 (99% identical), dog VPS29 (99% identical), guinea pig VPS29 (99% identical), macaque VPS29 (99% identical), mouse Vps29 (99% identical), pig VPS29 (99% identical), rabbit VPS29 (99% identical), rat Vps29 (98% identical), tropical clawed frog vps29 (97% identical), zebrafish vps29 (96% identical), Drosophila melanogaster Vps29 (84% identical), Caenorhabditis elegans vps-29 (59% identical).
Diseases named in the same sentence as VPS29 in open-access papers:
VPS29 is named in the same sentence as 27 diseases in open-access papers, as found by Europe PMC text mining. Sharing a sentence is not in itself a finding about the gene and the disease. The quoted sentences say what the papers report.
Parkinson’s (4 papers, 2022 to 2026). "VPS29 is a protein-coding gene associated with diseases such as Ritscher–Schinzel syndrome and late-onset Parkinson’s disease." (PMID 41554047, 2026). "VPS29 is important in endo-lysosomal trafficking, a process impacted in both Parkinson’s and Alzheimer’s diseases." (PMID 35960729, 2022). "These hub genes, particularly VPS35, VPS29, and GAK, hold potential not only as molecular drivers of Parkinson’s disease but also as candidates for developing non-invasive urinary biomarkers for early diagnosis and therapeutic targeting." (PMID 40130009, 2025).
Alzheimer disease (3 papers, 2022 to 2024). A progressive, neurodegenerative disease characterized by loss of function and death of nerve cells in several areas of the brain leading to loss of cognitive function such as memory and language. "With FRA10AC1 being well-connected by three binary interactors, namely VPS29, GATD3A, and EEF1D, to APP (amyloid β A4 precursor protein), the previously reported information characterizing two FRA10AC1 SNPs biomarkers of Alzheimer’s disease is further supported." (PMID 36980839, 2023).
schizophrenia (3 papers, 2021 to 2023). A major psychotic disorder characterized by abnormalities in the perception or expression of reality. "A recent study reported that a VPS29 variant associated with decreased VPS29 expression in the brain significantly increased the risk for schizophrenia, suggesting reduced VPS29 expression in the postmortem brains of schizophrenia is a biological mechanism underlying schizophrenia." (PMID 34659328, 2021). "As expected because of low sensitivity, this study identified only seven placental genes associated with schizophrenia, three of which are nonetheless replicated in our dataset (COQ10B, placenta-specific, and VPS29 and SEC11A, also associated with schizophrenia in brain)." (PMID 37188697, 2023). "Hence, the disruption of the VPS29 in our patient might contribute to the pathogenesis of her schizophrenia." (PMID 34659328, 2021).
influenza (2 papers, 2024 to 2025). An acute viral infection of the respiratory tract, occurring in isolated cases, in epidemics, or in pandemics; it is caused by serologically different strains of viruses (influenzaviruses) designated A, B, and C, has a 3-day incubation period, and usually lasts for 3 to 10 days. "We co-expressed the retriever complex-specific protein VPS26C, tagged with a double human influenza hemagglutinin (HA) tag, alongside the shared protein between retromer and retriever complexes, VPS29, tagged with a V5 tag." (PMID 38884339, 2024). "The case of VPS29 deficiency is of particular interest as there too the effects were virus-specific, causing inhibition of HCoV-OC43 or SARS-CoV-2, and facilitation of influenza infection." (PMID 39981379, 2025).
viral infection (2 papers, 2022 to 2025). "Notably, conditions that induce similar cell vacuolation, such as treatment with the phosphatidylinositol-3-phosphate 5-kinase inhibitor apilimod or deficient expression of VPS29, also inhibited viral infection." (PMID 39981379, 2025). "To elucidate the impact of VPS29 on viral infection, we next investigated the impact of VPS29 KO on normal endosomal function." (PMID 35229640, 2022). "That lack of additive effect of NH4Cl treatment in VPS29 KO cells suggests both conditions result in an analogous effect on viral infection." (PMID 35229640, 2022).
amyotrophic lateral sclerosis (1 paper, 2024). Amyotrophic lateral sclerosis (ALS) is a neurodegenerative disease characterized by progressive muscular paralysis reflecting degeneration of motor neurons in the primary motor cortex, corticospinal tracts, brainstem and spinal cord. "Following the identification of bis-1,3-phenyl guanylhydrazone 2a as an effective new compound for the treatment of amyotrophic lateral sclerosis, in this work we analyze the possible binding sites of this molecule to the VPS35/VPS29 dimer of the retromer complex." (PMID 38487369, 2024).
cardiac arrest (1 paper, 2024). Cessation of breathing and/or cardiac function. "Vitamin B12 may increase the risk of coronary atherosclerosis and cardiovascular death by reducing the levels of VPS29 and PSME1 proteins, while vitamin C may mitigate the risk of cardiac arrest by inhibiting the expression of the TPST2 protein." (PMID 39691718, 2024).
coronary atherosclerosis (1 paper, 2024). Atherosclerosis of the coronary vasculature. "Vitamin B12 may increase the risk of coronary atherosclerosis by inhibiting the expression of VPS29 and PSME1 proteins, and elevate the risk of death caused by heart disease through the suppression of PSME1 expression." (PMID 39691718, 2024). "Vitamin B12 may increase the risk of coronary atherosclerosis by inhibiting VPS29 (Mediated Effect=0.031, 95% CI: 0.030–0.032; Mediated Proportion=13.04%, 95% CI: 12.53%-13.56%) and PSME1 (Mediated Effect=0.101, 95% CI: 0.097–0.106; Mediated Proportion=42.75%, 95% CI: 40.88%-44.61%)." (PMID 39691718, 2024).
lysosomal storage disorders (1 paper, 2020). "Based on mouse models, synaptic dysfunction may be an early manifestation in lysosomal storage disorders similar to Vps29 mutant flies." (PMID 32286230, 2020). "Importantly, retromer participates in the trafficking of lysosomal hydrolases, and in the absence of Vps29, we documented accumulation of glucosylceramides along with ultrastructural evidence of brain lysosomal pathology similar to lysosomal storage disorders." (PMID 32286230, 2020).
multiple system atrophy (1 paper, 2016). Multiple system atrophy (MSA) is a neurodegenerative disorder characterized by autonomic failure (cardiovascular and/or urinary), parkinsonism, cerebellar impairment and corticospinal signs with a median survival of 6-9 years. "Genetic screening on the whole VPS26a, VPS26b, and VPS29 genes have identified other VPS mutations which may produce pathogenic effects both in PD and atypical parkinsonisms, such as PSP (Progressive Supranuclear Palsy), MSA (Multiple system atrophy), and Lewy body dementia (LBD)." (PMID 27932943, 2016).
nematode infection (1 paper, 2021). "In addition, VPS29 which was reportedly downregulated in RNA seq data showed a tendency to be lower in response to maternal nematode infection (p = 0.15)." (PMID 34764345, 2021).
proteinopathies (1 paper, 2026). "In aggregate, these findings provide evidence that TDP-43 dysfunction modulates the APA of retromer component VPS35, reducing the expression of VPS35 and VPS29, thereby uncovering a potential mechanistic link between TDP-43 loss of function, APA, and retromer dysfunction in TDP-43 proteinopathies." (PMID 41490046, 2026).
retinal degeneration (1 paper, 2020). Degeneration of the retina. "Similar results were obtained for the Vps29 retinal degeneration phenotype." (PMID 32286230, 2020). "Age- and light-dependent retinal degeneration in the absence of Vps29 was further confirmed by histology, and this phenotype was also reversed by introduction of the Vps29 genomic rescue construct." (PMID 32286230, 2020). "Interestingly, in the Drosophila visual system, we found that raising Vps29 or Vps35 mutants in the dark rescued retinal degeneration but not synaptic transmission defects, consistent with an uncoupling of retromer requirements in these two spatially distinct processes." (PMID 32286230, 2020).
infection (7 papers, 2015 to 2025). The state of being infected such as from the introduction of a foreign agent such as serum, vaccine, antigenic substance or organism. "Knockdown of retromer subunit VPS35 or VPS29 or infection with HPV16 PsV harboring retromer binding site mutations in L2 causes HPV accumulation in endosomes, indicating that the HPV-retromer interaction is required for endosome exit." (PMID 37703297, 2023). "Indeed, we observed a strong inhibition of rVSV/EBOV-GP infection upon either cathepsin inhibition or loss of VPS29." (PMID 35229640, 2022). "If this were indeed the case, then VPS29 KO should impair infection mediated by ebolavirus (EBOV) glycoprotein (GP), which is known to require processing by endosomal cathepsins." (PMID 35229640, 2022). "One candidate gene, VPS29, a component of the retromer complex, was required for infection by HCoV-OC43, SARS-CoV-2, other endemic- and pandemic-threat coronaviruses, as well as ebolavirus." (PMID 35229640, 2022). "In particular, we show that the retromer subunit protein VPS29 is required for productive infection by diverse CoVs in a variety of cell types." (PMID 35229640, 2022). "Indeed, in several instances, VPS29 KO and/or cathepsin inhibition resulted in undetectable infection by SARS-CoV-2R683G, SARS-CoV, and the SARS-like bat/pangolin CoVs." (PMID 35229640, 2022). "Thus, distinct effector functions of VPS29 may have different infection-enhancing and inhibiting properties, with the overall effect depending on viral and/or cell type-specific characteristics." (PMID 35229640, 2022). "Many of the hits were associated with intracellular transport or endosome activity, including VPS29, the CCDC22/CCDC93/COMMD3 (CCC) complex, and the WDR81/91 complex, suggesting a requirement for these functions in HCoV-OC43 infection." (PMID 35229640, 2022). "In this experiment, HeLa and HaCaT cells were transfected with siRNA targeting the retromer subunit Vps29, infected with HPV16.L2F two days later, and subjected to PLA at various times post-infection." (PMID 25693203, 2015). "However, in VPS29 KO cells, enlarged endosomes contained many rVSV/SARS-CoV-2NG-P punctae at 60 min after infection." (PMID 35229640, 2022). "We next investigated whether the VPS29/CCC complex and the WDR81/91 were required for infection by a diverse panel of respiratory viruses, including coronaviruses." (PMID 35229640, 2022). "Similarly, infectivity assays utilizing rVSV/SARS-CoV-2 also revealed diminished infectivity upon cathepsin inhibition in parental HT1080, but no impairment of infection upon cathepsin inhibition in VPS29 KO cells." (PMID 35229640, 2022). "However, cathepsin inhibition did not further decrease infection of VPS29 KO cells." (PMID 35229640, 2022). "Indeed, infection by HCoVs that use three distinct receptors was inhibited by VPS29/CCC KO, while there was no VPS29/CCC requirement for infection by IAV, adenovirus, or RSV, which should otherwise also be dependent on cell surface expression of their respective receptors." (PMID 35229640, 2022).
cancer (3 papers, 2020 to 2025). A tumor composed of atypical neoplastic, often pleomorphic cells that invade other tissues. "Although alterations in other retromer components, such as VPS35 and VPS29, have been associated with cancer and neurodegenerative diseases, the role of VPS26A in malignancies, particularly LIHC, has not been thoroughly examined." (PMID 40731912, 2025). "We found that mutations predicted to disrupt the interaction between the NT “belt” and the CT region of VPS35L, including W6D, S829E, and the cancer-derived mutation G902E, abolished the binding to VPS29 without affecting VPS26C binding." (PMID 37397996, 2023). "In contrast, the cancer-derived mutation G325E specifically disrupted VPS35L binding to VPS26C, without affecting the binding to VPS29 or CCC components." (PMID 37397996, 2023).
neurodegenerative disease (3 papers, 2020 to 2025). A disorder of the central nervous system characterized by gradual and progressive loss of neural tissue and neurologic function. "Targeting the retromer for therapeutic manipulation in neurodegenerative disease is one promising approach, given the availability of small molecule chaperones that bind Vps29." (PMID 32286230, 2020).
VPS29 also shares sentences with these, for which no sentence is quoted: malaria (2 papers); tumor (2); cardiovascular disease (1); frontotemporal dementia (1); heart disease (1); Hernia (1); late-onset Parkinson disease (1); metabolism disorder (1); phlebitis (1); Ritscher-Schinzel syndrome (1); Thrombophlebitis (1).